WNT3 (Wnt family member 3)
Description:
Ligand for members of the frizzled family of seven transmembrane receptors (Probable). Functions in the canonical Wnt signaling pathway that results in activation of transcription factors of the TCF/LEF family. Required for normal gastrulation, formation of the primitive streak, and for the formation of the mesoderm during early embryogenesis. Required for normal formation of the apical ectodermal ridge (By similarity). Required for normal embryonic development, and especially for limb development.
Synonyms: INT4; MGC131950; MGC138321; MGC138323; TETAMS
Tractability: Small molecule: a structure with a bound ligand is known; it belongs to a druggable protein family. Antibody: UniProt places it where antibodies can reach, with high confidence; its Gene Ontology location is reachable by antibodies, with high confidence; UniProt predicts a signal peptide or a membrane-spanning region. PROTAC: a small molecule that binds it is known.
Target class: Secreted protein
Gene: Protein-coding gene on chromosome 17 (46,762,506 to 46,833,154, reverse strand). Ensembl gene ENSG00000108379.
Subcellular location: Secreted, extracellular space, extracellular matrix; Secreted
Subcellular location (Human Protein Atlas): Vesicles; Predicted to be secreted
Pathways (Reactome):
Signal Transduction: Class B/2 (Secretin family receptors); TCF dependent signaling in response to WNT; WNT ligand biogenesis and trafficking
Gene Ontology:
Molecular function: frizzled binding; protein binding; receptor ligand activity; cytokine activity; protein domain specific binding; signaling receptor binding
Biological process: canonical Wnt signaling pathway; cell morphogenesis; limb bud formation; mammary gland epithelium development; midbrain dopaminergic neuron differentiation; positive regulation of gene expression; positive regulation of osteoblast differentiation; regulation of mesenchymal stem cell differentiation; regulation of neurogenesis; stem cell proliferation; cell fate commitment; cellular response to retinoic acid; neuron differentiation; anatomical structure morphogenesis; animal organ development; limb development; positive regulation of cell differentiation; positive regulation of Wnt signaling pathway; system development; Wnt signaling pathway
Cellular component: extracellular region; endocytic vesicle membrane; endoplasmic reticulum lumen; extracellular exosome; Golgi lumen; plasma membrane; Wnt signalosome; bounding membrane of organelle; endoplasmic reticulum; extracellular matrix
Genetic constraint (gnomAD): Loss-of-function variants: 7 observed, 35.86 expected, observed/expected ratio (o/e) 0.2, 90% interval 0.11 to 0.37. The upper end of that interval is the gene's LOEUF score, 0.37, which puts it in group 1 of 6, group 1 being the genes least tolerant of losing a copy. Missense variants: 267 observed, 509.99 expected, observed/expected ratio (o/e) 0.52, 90% interval 0.47 to 0.58. Synonymous variants: 212 observed, 221.51 expected, observed/expected ratio (o/e) 0.96, 90% interval 0.86 to 1.07.
Gene-disease validity (ClinGen):
ClinGen rates the evidence that WNT3 causes each of these diseases.
tetraamelia syndrome 1 (autosomal recessive): Limited.
Homologues: Orthologues: chimpanzee WNT3 (100% identical), macaque WNT3 (100% identical), guinea pig WNT3 (99% identical), pig WNT3 (99% identical), mouse Wnt3 (99% identical), rabbit WNT3 (92% identical), tropical clawed frog wnt3 (90% identical), zebrafish wnt3 (90% identical), dog WNT3 (77% identical), rat Wnt3 (76% identical). Paralogues in human: WNT3A (83% identical), WNT4 (47% identical), WNT1 (45% identical), WNT5B (45% identical), WNT2 (45% identical), WNT5A (45% identical), WNT2B (44% identical), WNT7B (43% identical), WNT7A (43% identical), WNT16 (41% identical), WNT6 (41% identical), WNT10A (39% identical), and 6 more.
Diseases named in the same sentence as WNT3 in open-access papers:
WNT3 is named in the same sentence as 122 diseases in open-access papers, as found by Europe PMC text mining. Sharing a sentence is not in itself a finding about the gene and the disease. The quoted sentences say what the papers report.
breast cancer (20 papers, 2013 to 2025). A primary or metastatic malignant neoplasm involving the breast. "In performing the analysis of AF with breast cancer (ER+), WNT3 and XBP1 were obtained based on eQTLGen." (PMID 39170695, 2024). "It is thus interesting that Wnt3 can promote EMT in breast cancer cells while in the sea cucumber, it is overexpressed beginning at 1-dpe, which is slightly earlier than the EMT timeline." (PMID 36833237, 2023). "TGF-β (TGFBR1 is TGF-β receptor 1) can induce the upregulation of Wnt3 and the β-catenin pathway in breast cancer cells." (PMID 34225723, 2021). "Previous studies reported that LGK alone significantly reduces the growth of a murine mouse mammary tumor-Wnt3 model." (PMID 34367990, 2021). "In breast cancer, Wnt3 overexpression can promote EMT-like phenotype through activating the Wnt/β-catenin signaling pathway." (PMID 34385891, 2021). "In breast cancer, Wnt3 over-expression activates Wnt/β-catenin pathway which leads to trans-activation of EGFR and promotes EMT in trastuzumab-resistant cells." (PMID 29986466, 2018). "Recent studies advocate the specific targeting of WNT3, indicating its potential in countering Trastuzumab resistance, which may be of therapeutic benefit for patients with breast cancer overexpressing HER2." (PMID 38711026, 2024). "Wnt3 expression in HER2 breast cancer cells leads to pEMT and decreased sensitivity to trastuzumab." (PMID 36788501, 2023). "In breast cancer, co-expression of Wnt ligands, including Wnt3, Wnt4, Wnt5a, and Wnt7a, leads to the activation of Wnt pathway, while in colorectal cancer, mutation or loss function of the APC gene or protein is more likely to be the reason for Wnt pathway activation." (PMID 29986466, 2018). "It has been reported that overexpression of WNT3 activates the Wnt/β-catenin signaling pathway, resulting in transactivation of EGFR and provoking an EMT-like phenotype, which in turn could underlie the trastuzumab resistance of HER2+ breast cancers." (PMID 36831511, 2023). "Some researchers have found similar phenomena in breast cancer cell lines, esophageal squamous cell carcinoma cell lines, and osteoarthritic chondrocyte cell lines, in which expression of nuclear β-catenin was decreased and the Wnt/β-catenin signaling pathway was suppressed after knockdown of WNT3." (PMID 34608506, 2021). "We show in this study that the knockdown of MALAT1 reduced the number of invaded cells induced by exogenous Wnt3 protein in HER2+ breast cancer cells, which suggests that MALAT1 may also interact with Wnt3 to induce cell invasiveness and decrease trastuzumab sensitivity in HER2+ breast cancer cells." (PMID 32708561, 2020). "The WNT ligands WNT1 and WNT3 are involved in the activation of WNT/β-catenin/TCF signaling to promote mammary tumorigenesis, and stem cell-like properties in breast cancer." (PMID 38380359, 2024). "Wnt3 overexpression activates the Wnt/β-catenin signaling pathway inducing the EMT process, which affords HER2-positive breast cancer cells obtain trastuzumab-resistant characteristics." (PMID 37538794, 2023). "Prognostic value of WNT3 d and WNT11 e mRNA levels in human breast cancer, data obtained from the KM-plotter." (PMID 31462314, 2019). "b mRNA expression of WNT3A, WNT3, WNT5A, WNT5B, and WNT11 in five different breast cancer subtypes based on bc-GenExMiner v4.1 according to the Sørlie’s subtypes (****p < 0.0001; Red star: the former > the latter; Green Star: the former < the latter)." (PMID 31462314, 2019). "Recently, expression of Wnt3 has been shown to activate WP and promoted EMT-like phenotype in trastuzumab-resistant HER2-overexpressing breast cancer cells." (PMID 24143235, 2013). "Activation of Wnt/β-catenin pathway will induce trastuzumab resistance in breast cancer cells with HER2 overexpression, thus, knocking out Wnt3 by siRNA can result in downregulation of EMT-related expression and restoration of trastuzumab’s inhibitory effect on cell growth." (PMID 41211430, 2025).
breast cancer (continued). "Furthermore, activation of WNT3 was observed to stimulate the WNT/β-catenin pathway and an epithelial-mesenchymal transition (EMT)-like phenotype in trastuzumab-resistant HER2-overexpressing breast cancer cells." (PMID 38711026, 2024). "Furthermore, treatment of ER− breast cancer cells with pictilisib, a strong PI3Kα/δ and modest PI3Kβ/γ inhibitor, increased mRNA expression of Wnt ligands including WNT2B, WNT3, WNT5B and WNT10A, as well as phosphorylation of LRP6 and β-catenin nuclear translocation." (PMID 37471270, 2023).
gastric cancer (12 papers, 2017 to 2024). A primary or metastatic malignant neoplasm involving the stomach. "Similar to Wnt3, Flot2 is linked to tumour development and proliferation, and its expression is increased in gastric cancer (GC)." (PMID 36040316, 2022). "More recently, we have shown that Wnt3 is transported intercellularly via cytonemes and facilitates tumor progression in gastric cancer." (PMID 37722040, 2023). "The number and length of Wnt3 cytonemes correlate with gastric cancer cell survival and proliferation." (PMID 37722040, 2023). "Here, we demonstrate that gastric cancer cells utilise cytonemes to transport Wnt3 intercellularly to promote proliferation and cell survival." (PMID 36040316, 2022). "Together with the Wnt co-receptor and cytoneme initiator Ror2, Flot2 determines the number and length of Wnt3 cytonemes in gastric cancer." (PMID 36040316, 2022). "On the other hand, substantial evidence has shown that Wnt-3 is a key regulator of cell proliferation and metastasis in colorectal cancer, gastric cancer development, and malignant melanoma." (PMID 33014112, 2020). "On the other hand, the overexpression of Wnt ligands has been reported in different cancers—for instance, Wnt1 and Wnt5 in hepatocellular, colon or stomach cancers, Wnt5 in lung cancer and Wnt3 in prostate tumors, as well as Wnt3 and Wnt5 in oral cancer." (PMID 32630122, 2020). "Similarly, the lipid-modified Wnt proteins Wnt8a and Wnt3 are disseminated by cytonemes in zebrafish and gastric cancer cells, respectively." (PMID 38123680, 2024). "Specifically, Wnt3 spreading in gastric cancer is promoted by Flot2-positive cytonemes." (PMID 37722040, 2023). "Consequently, Flot2 function correlates positively with colony formation, suggesting that Flot2-dependent Wnt3 cytonemes are essential in promoting proliferation and activity of gastric cancer stem cells." (PMID 36040316, 2022). "We previously reported that gastric tumors also expressed elevated levels of Wnt3, and silencing Wnt3 in gastric cancer cells could block cell proliferation and induce apoptosis through targeting the canonical Wnt pathway." (PMID 32923386, 2020). "Similarly, Wnt3 is loaded on cytonemes in gastric cancer to facilitate tumour proliferation." (PMID 38123680, 2024). "Emerging evidence has demonstrated that Wnt/β‐catenin is activated after gastric cancer and plays a critical role in promoting invasion and migration through overexpressing or increasing the functions of several components of the Wnt pathway such as Wnt1, Wnt2, Wnt3, Wnt5a, Fzd‐3, CTNNB1 and LRP6." (PMID 28994231, 2018). "Interestingly, we could not detect the actin motor myosin 10 (MYO10), which regulates the formation and elongation of filopodia on WNT7A-positive dendritic filopodia, suggesting a difference from the Wnt8a cytonemes observed in zebrafish gastrulation or WNT3 cytonemes in human gastric cancer." (PMID 39576204, 2024). "In gastric cancer cell lines OKAJIMA, TMK1, MKN7, MKN45, and MKN74, the expression of WNT3 mRNA has been observed." (PMID 38800305, 2024). "Growth of intestinal organoids and their differentiation of Paneth cells depends on Paneth cell-derived Wnt3, and absence of Wnt3 represses both expression of β-catenin and proliferation of gastric cancer cells." (PMID 28846687, 2017).
colorectal cancer (10 papers, 2018 to 2025). A primary or metastatic malignant neoplasm that affects the colon or rectum. "We previously found that (pro)renin receptor ((P)RR) augments Wnt3 protein without affecting Wnt3 gene transcription in colorectal cancer (CRC) cells, thus contributes to CRC initiation." (PMID 36597142, 2023).
esophageal squamous cell carcinoma (10 papers, 2019 to 2024). Esophageal squamous cell carcinoma (ESCC) is a type of esophageal carcinoma (EC) that can affect any part of the esophagus, but is usually located in the upper or middle third. "Other noteworthy instances include circRNA_100367, which regulates radiation sensitivity in esophageal squamous cell carcinomas via the miR-217/Wnt3 pathway." (PMID 38806577, 2024). "In radioresistant esophageal squamous cell cancer cells, circRNA_100367 bound to miR-217 and regulated Wnt3 expression, thereby affecting radioresistance." (PMID 36276285, 2022). "In addition, miR-217/Wnt3 was shown to be a downstream target of circRNA_100367 in the regulation of ESCC (esophageal squamous cell carcinoma) radiosensitivity." (PMID 37372440, 2023).
melanoma (10 papers, 2008 to 2025). A malignant, usually aggressive tumor composed of atypical, neoplastic melanocytes. "Wnt3 also regulates differentiation in B16 melanoma cells and reduces the proliferation of human melanoma cells." (PMID 25818589, 2015). "RNAi of candidate Wnts identifies Wnt1, Wnt2, Wnt3, and Wnt7b as the specific isoforms mediating autocrine Wnt signaling in tumor cell lines M14 (melanoma), NCI-H23 (NSCLC), PA-1 (teratocarcinoma), and Hs578T (breast), respectively." (PMID 20856934, 2010). "Among them, WNT3 and WNT4 were implied as melanoma tumor suppressors; WNT7A and WNT10A displayed contribution to the female reproductive system adenocarcinomas." (PMID 35850748, 2022). "For instance, WNT3 and WNT4 are implied as a tumor suppressor of melanoma." (PMID 35850748, 2022). "WNT3 and WNT5A were detected at a much higher level than WNT8 and WNT11, so we investigated further whether WNT3 and WNT5A signal through FZD7 in melanoma cells." (PMID 26808375, 2016). "Interestingly, treatment of MA-2 human melanoma cells with WNT3 or LiCl increased canonical WNT signalling, and decreased JNK (non-canonical Wnt signalling) in cells with FZD7 knockdown, suggesting that FZD7 suppresses the canonical Wnt pathway in melanoma cells." (PMID 27196929, 2016). "On the other hand, ectopic overexpression of β‐catenin stimulates melanoma cell growth in a MITF‐dependent manner, suggesting an altered transcriptional activity of β‐catenin in the absence of a Wnt3 signalling context." (PMID 25818589, 2015).
lung carcinoma (8 papers, 2014 to 2025). "AvL-EtOH treatment inhibits the mRNA expression of Wnt3 in lung cancer cells." (PMID 37110139, 2023).
hepatocellular carcinoma (6 papers, 2011 to 2022). A malignant tumor that arises from hepatocytes. "Studies have shown that WNT3 is upregulated in human breast, rectal, lung, gastric, and hepatocellular cancer tissues and plays a key role in the occurrence and development of these tumors by activating the Wnt/β-catenin signaling pathway." (PMID 34608506, 2021). "Our studies above are in agreement with previously reported Wnt3-Fzd7 binding in intestinal stem cells and the functional interaction between Wnt3 and Fzd7 in hepatocellular carcinoma cells." (PMID 33525513, 2021). "In hepatocellular carcinoma cells, the functional interaction between Wnt3 and FZD7 enhances proliferative rate." (PMID 26716419, 2016). "In addition, the functional interaction between Wnt3 and Fzd7 led to the activation of the Wnt/β-catenin signaling pathway in hepatocellular carcinoma cells." (PMID 33525513, 2021). "In EpCAM+ hepatocellular carcinoma (HCC), as well as advanced cirrhosis liver tissues, autocrine Wnt signaling was activated, as evidenced by elevated expression of Wnt3, β-catenin, c-Myc and CCND1." (PMID 36369033, 2022). "In hepatocellular carcinoma, upregulation of FZD7 was positively correlated with nuclear accumulation of wild-type β-catenin, and interaction between WNT3 and FZD7 could lead to activation of canonical WNT signaling pathway." (PMID 29029485, 2017).
colon cancer (5 papers, 2016 to 2023). "Based on the TCGA dataset analysis, higher transcriptional level of Wnt3 is found in primary lesions of colon cancer in comparison to that of paracancerous normal tissues." (PMID 36597142, 2023). "Wnt3 was highly expressed in colon cancer tissues, and autocrine Wnt3 secretion via Evi/Wls was required to maintain the Wnt activity in colon cancer cells." (PMID 32923386, 2020). "However, there is little association between the transcriptional levels of ATP6AP2 and Wnt3 in colon cancer (r = 0.25)." (PMID 36597142, 2023). "Interfering with the secretion of Wnt3 could impair the growth of colon cancer cells in vitro and in vivo." (PMID 32923386, 2020). "In addition, we have also measured the effect of CHST15 siRNA on the expression of EMT markers such as E-cadherin, vimentin, BMP7 and Wnt3 using TGF-β-stimulated colon cancer cell line and identified a significant suppression of these markers in the CHST15 siRNA treated cells." (PMID 27410685, 2016). "It has been reported that Paneth cell-specific deletion of Wnt3 leads to a reduction in small intestinal tumors but not colonic tumors in ApcMin/+ mice." (PMID 36739585, 2023). "In colon cancer cells, (P)RR dramatically inhibits the NEDD4L-mediated Wnt3 protein ubiquitination." (PMID 36597142, 2023).
COVID-19 (5 papers, 2022 to 2023). A disease caused by infection with severe acute respiratory syndrome coronavirus 2. "In addition, both NSF and Wnt3 are confirmed as putative causal genes for COVID-19 severity." (PMID 37426090, 2023). "While WNT3 is involved in intelligence and multiple psychiatric conditions, its roles in COVID-19 phenotypes are more elusive and likely defined by indirect relationships with blood–brain barrier permeability." (PMID 37286376, 2023). "The study of WNT3 involvement in the intersection of COVID-19 and cognitive phenotypes closely follows that of MAPT." (PMID 37286376, 2023). "This may explain why immune-related genes such as WNT3 were mainly identified to be shared with COVID-19 severity." (PMID 37636041, 2023). "In addition, we identified 14 other diseases associated with COVID-19 by sharing four DEGs (i.e., DMD, C2CD3, WNT3 and AHDC1) which were most prevalent in COVID-19." (PMID 36059456, 2022). "In this study, we found 14 other diseases associated with COVID-19 by sharing four DEGs (i.e., DMD, C2CD3, WNT3, and AHDC1) most prevalent in COVID-19." (PMID 36059456, 2022).
Amelia (4 papers, 2016 to 2025). Congenital absence (aplasia) of one or more limbs. "Mutations in WNT3 are well-known causes of syndromic tetra-amelia with CLP (OMIM# 273395), but the disruption of this gene has recently also been described as involved in non-syndromic OFC with TA." (PMID 27699475, 2016). "For example, mutations in the WNT3 gene dominate autosomal recessive tetra-amelia with CL." (PMID 30704473, 2019). "To date, TBX5 has been associated with upper amelia, TBX4 with lower amelia, and WNT3, WNT7A and RSPO2 with tetra-amelia syndromes in humans (and cattle, for RSPO2)." (PMID 40131457, 2025).